TRAF4 (TNF receptor associated factor 4)
Diseases named in the same sentence as TRAF4 in open-access papers (continued):
Sharing a sentence is not in itself a finding about the gene and the disease.
fungal infection (1 paper, 2023). "We have determined that TRAF4 was ubiquitinated at K338 to form K63-linked polyubiquitin chains, which is important for the induction of immune effectors after fungal infection." (PMID 36537797, 2023). "TRAF4-deficient mosquitoes were more sensitive to fungal infection, indicating TRAF4 to be the adaptor protein that activates the Toll pathway." (PMID 36537797, 2023). "Our results showed that, after fungal infection, OTU7B interacts with TRAF4 and causes the removal of its ubiquitin chains." (PMID 36537797, 2023). "Because we have determined that OTU7B forms a complex with TRAF4 after fungal infection, we studied the role of TRAF4 in mosquito immunity." (PMID 36537797, 2023). "We have shown that fungal infection triggers ovarian tumor (OTU) domain-containing protease (OTU7B) expression, which in turn removes the K63-linked polyubiquitin chains of TRAF4." (PMID 36537797, 2023). "Immunostaining assays showed that after fungal infection, compared with wild-type mosquitoes, the Rel1 signal in nuclei was very weak in TRAF4+/− mosquitoes, suggesting that TRAF4 promotes Rel1 translocation into nucleus." (PMID 36537797, 2023). "qRT-PCR results showed that the mRNA levels of two selected AMPs were significantly reduced in TRAF4+/− mosquitoes after fungal infection, which was similar with that of TRAF4 RNAi mosquitoes, suggesting that TRAF4 activates the expression of AMP genes." (PMID 36537797, 2023). "We also examined the relationship between OTU7B and TRAF4 in the modulation of mosquito immune response after fungal infection." (PMID 36537797, 2023). "The immunoblotting analysis revealed that the K63-linked polyubiquitin chains were obviously accumulated in OTU7B−/− mosquitoes after fungal infection, suggesting that OTU7B is responsible for the removal of K63-linked polyubiquitin chains from TRAF4." (PMID 36537797, 2023). "aegypti fat bodies after fungal treatment, while in OTU7B−/− mosquitoes, after fungal infection, the localization of TRAF4 is different from that of wild-type mosquitoes, indicating that OTU7B restricts the distribution of TRAF4 in the immune response." (PMID 36537797, 2023). "OTU7B interacts with the Toll adapter TRAF4 after fungal infection." (PMID 36537797, 2023). "We have shown that the fungal infection triggers the expression of DUB OTU7B, which enzymatically removes K63-linked polyubiquitin chains from the Toll pathway adapter TRAF4, preventing the translocation of the NF-κB factor Rel1 into the nucleus, and mosquitoes become more sensitive to fungi." (PMID 36537797, 2023). "We first evaluated the survival rate of TRAF4+/− mosquitoes after fungal infection." (PMID 36537797, 2023). "We first investigated the responses of TRAF4 to fungal infection." (PMID 36537797, 2023). "Thus, OTU7B interacts with the Toll adapter TRAF4 after fungal infection." (PMID 36537797, 2023).
gastric carcinoma (1 paper, 2018). A carcinoma that arises from epithelial cells of the stomach. "The expression of lncRNA AC010761.9 and TRAF4 in gastric carcinoma was positively correlated, which suggests that lncRNA AC010761.9 may play a biological role in the development and progression of GA possibly by regulating the expression of TRAF4." (PMID 29499718, 2018).
in situ carcinoma (1 paper, 2008). A malignant epithelial neoplasm which is confined to the epithelial layer without evidence of further tissue invasion. "In vivo, TRAF4 is consistently found at TJs in normal human mammary epithelia as well as in well-differentiated in situ carcinomas." (PMID 18953416, 2008).
influenza (1 paper, 2023). An acute viral infection of the respiratory tract, occurring in isolated cases, in epidemics, or in pandemics; it is caused by serologically different strains of viruses (influenzaviruses) designated A, B, and C, has a 3-day incubation period, and usually lasts for 3 to 10 days. "IL-17 signaling through the non-canonical IL-17 receptor EGFR activates the scaffold protein TRAF4 more than TRAF6 during alleviation of lung inflammation in severe influenza." (PMID 37270623, 2023). "Our results suggest that viral neuraminidase-activated TGF-β of the Th1 cells guides the Th17 evolution, and IL-17 signaling through the non-canonical IL-17 receptor EGFR activates the scaffold protein TRAF4 more than TRAF6 during alleviation of lung inflammation in severe influenza." (PMID 37270623, 2023).
invasive carcinoma (1 paper, 2008). A carcinoma that is not confined to the epithelium, and has spread to the surrounding stroma. "Since TRAF4 is never addressed to the plasma membrane in invasive carcinomas, it can be hypothesized that this function on ERK might be constitutively turn on in malignant conditions." (PMID 18953416, 2008).
ischemic stroke (1 paper, 2023). A stroke disorder caused by obstruction of blood flow to the brain, due to thrombotic (local blood clot formation) or embolic (due to a blood clot or other material traveling from another site) event. "In ischemic stroke patients, miR-4443 interacts with the 3’-UTR of TRAF4 and inhibits TRAF4 protein expression." (PMID 37909033, 2023).
liver cancer (1 paper, 2020). An epithelial or non-epithelial malignant neoplasm that arises from the liver. "It inhibits liver cancer cell proliferation and migration by targeting TRAF4." (PMID 32760226, 2020).
lymphocytic leukaemia (1 paper, 2022). "Glucocorticoid-mediated E4BP4 promotes apoptotic effects in CEM lymphocytic leukaemia cells through upregulation, whereas TRAF4 expression in contrast to E4BP4 inhibits apoptosis in lymphocytic leukaemia cells." (PMID 35242717, 2022).
lymphoma (1 paper, 2019). A malignant (clonal) proliferation of B- lymphocytes or T- lymphocytes which involves the lymph nodes, bone marrow and/or extranodal sites. "Hyperexpression of TRAF4 has been described in human marginal zone lymphomas, highlighting its role as transcription factor in lymphoma pathogenesis." (PMID 30908498, 2019).
mastocytosis (1 paper, 2016). A clonal myeloproliferative neoplasm characterized by the proliferation and accumulation of neoplastic mast cells in one or multiple organs or organ systems. "The observation of a higher expression of TRAF4 related to Th2 inflammation confirms another observation of the role of the IL-13 gene polymorphism in the pathogenesis of mastocytosis and frequent symptoms of food hypersensitivity affecting this group of patients." (PMID 27086366, 2016). "In conclusion, the TRAF4 expression was higher in mastocytosis patients with food hypersensitivity in their medical history." (PMID 27086366, 2016). "The TRAF4 expression was higher in mastocytosis patients with food hypersensitivity in their medical history, the B3GAT1 expression was lower in mastocytosis patients with IVA in history." (PMID 27086366, 2016). "The results of the study indicate the increased expression of TRAF4 in mastocytosis patients with food hypersensitivity and decreased expression of B3GAT1 in mastocytosis patients with IVA." (PMID 27086366, 2016). "Significant differences in gene expression were found for TRAF4 (p = 0.008) in the comparison of the mastocytosis patients with and without concomitant food hypersensitivity." (PMID 27086366, 2016). "Significant differences in the gene expression were found for TRAF4 (p = 0.008) in the comparison of the mastocytosis patients with and without concomitant food hypersensitivity." (PMID 27086366, 2016).
metastatic cancer (1 paper, 2025). A carcinoma which has spread from the original site of growth to another anatomic site. "Finally, we have identified a natural product capable of inhibiting the nuclear translocation of TRAF4 from the plasma membrane, presenting a novel and promising therapeutic approach for the treatment of metastatic cancer." (PMID 39716976, 2025).
metastatic prostate carcinoma (1 paper, 2022). A carcinoma that arises from the prostate gland and has spread to other anatomic sites. "The tumor suppressor microRNA in miR-29a is one of the regulators of TRAF4 expression in metastatic prostate cancer, and the TRAF4 mRNA and protein expression is inversely correlated with miR-29a." (PMID 35242717, 2022). "TRAF4 is an E3 ubiquitin ligase highly expressed in metastatic prostate cancer." (PMID 35242717, 2022).
nasopharyngeal carcinoma (1 paper, 2024). A carcinoma arising from the nasopharyngeal epithelium. "Thus, a combinatorial approach of targeting TRAF4 or its downstream molecule, such as Akt with IR, would elevate the therapeutic effect of irradiation on nasopharyngeal carcinoma, which provides novel insights into rational cancer treatment." (PMID 38164179, 2024).
pancreatic cancer (1 paper, 2024). "In addition, TRAF4, TRAF5, TRAF6, and TRAF7 demonstrate correlations with the degree of pancreatic cancer differentiation." (PMID 38825674, 2024).
postmenopausal osteoporosis (1 paper, 2019). Metabolic disorder associated with fractures of the femoral neck, vertebrae, and distal forearm. "To evaluate the possible functional significance of TRAF4 in bone metabolism in vivo, we produced OVX rats as an animal model of postmenopausal osteoporosis." (PMID 31076633, 2019).
sarcoma (1 paper, 2024). A usually aggressive malignant neoplasm of the soft tissue or bone. "Finally, TRAF4 was associated with oncogenic effects in ACC (OS: n = 79, p = 0.003), HNSC (OS: n = 501, p = 0.023), KIRC (OS: n = 531, p = 0.005), LIHC (OS: n = 368, p = 0.032), and Sarcoma (SARC) (OS: n = 260, p = 0.036)." (PMID 38825674, 2024).
spina bifida (1 paper, 2013). A congenital neural tube defect in which vertebrae are not fully formed. "TRAF4 involvement in NTC has also been described in mice as TRAF4-deficient mice exhibit NTC defects giving rise to mild spina bifida phenotypes and embryonic lethality." (PMID 24311986, 2013).
squamous cell carcinoma of the head and neck (1 paper, 2013).
cancer (54 papers, 2008 to 2025). A tumor composed of atypical neoplastic, often pleomorphic cells that invade other tissues. "TRAF4 is predominantly expressed in the ESCC cancer cells described in the cytoplasm at high expression, and TRAF4 overexpression is an independent risk factor for the overall prognosis of patients." (PMID 35242717, 2022). "TRAF4 has long been found to be overexpressed in various carcinomas, whereas EGFR has been shown to be associated with NSCLC." (PMID 35748027, 2022). "Tumor necrosis factor receptor‐associated factor 4 (TRAF4) is overexpressed in a variety of carcinomas of different origins, but its role in tumorigenesis remains incompletely understood." (PMID 35748027, 2022). "We identified several candidates, including the tumour necrosis factor receptor-associated factor 4 (TRAF4), as candidates for conferring resistance to anti-cancer drugs in CSCs of gastrointestinal cancer." (PMID 29343747, 2018). "About 42% (44/105) of the coding-altering mutations of the TRAF4 gene are recurrent and detected in at least two cancer patients, including mostly missense mutations (89%, 39/44), 3 truncations, 1 frameshift deletion, and 1 in frame deletion." (PMID 30294322, 2018). "There are 123 different mutations of TRAF4 detected in human cancers, comprising 85% (105/123) mutations that cause changes in the amino acid sequence of TRAF4 and 15% (18/123) coding silent mutations." (PMID 30294322, 2018). "The cancer-associated TRAF4 protein has a TRAF domain that is a bona fide phosphoinositide-binding domain and involved in the modulation of tight junctions and cell migration." (PMID 24311986, 2013). "Tumor necrosis factor (TNF) receptor-associated factor 4 (TRAF4) is frequently overexpressed in carcinomas, suggesting a specific role in cancer." (PMID 24311986, 2013). "Tumor Necrosis Factor Receptor-Associated Factor 4 (TRAF4) is a gene whose expression is altered in cancers." (PMID 24212830, 2011). "It is noteworthy that the pathways regulated by Ato target genes, as well as many of the target genes themselves or their mammalian homologues, such as sens, dap, Traf4, and Mmp2 are implicated in cancer." (PMID 20668662, 2010). "Importantly, TRAF4 deficiency significantly decreases the proliferation, colony formation, and tumorigenesis of cancer cells under treatment with chemotherapeutic agents." (PMID 32357935, 2020). "This suggests that TRAF4 overexpression may play causal roles in cancer initiation, progression and metastasis." (PMID 30294322, 2018). "The elevated expression of TRAF4 in many carcinomas suggests that this protein might have an important role in cancer which could be linked to cell polarity or apoptosis regulation." (PMID 24212830, 2011). "Experiments using either xenograft or genetic mouse models illustrated that deficiency in Skp2, TRAF6 or TRAF4 results in suppression of cancer development in vivo, pointing to the critical role of distinct E3 ubiquitin ligases in Akt-mediated biological functions and cancer progression." (PMID 25309720, 2014). "To ascertain that nuclear localization of TRAF4 is not an artifact resulting from overexpression, we examined endogenous nuclear TRAF4 expression across various cancer types." (PMID 39716976, 2025). "This study demonstrated a positive correlation between the expression of nuclear TRAF4 and both tumor grades and stemness signatures in human cancer tissues." (PMID 39716976, 2025). "Beyond cancer, curcumin increased m6A on TRAF4 mRNA by inhibiting ALKBH5, which in turn enhanced YTHDF1-dependent TRAF4 translation and suppressed adipogenesis." (PMID 41322307, 2025). "This study highlights the critical role of nuclear TRAF4 in regulating tumor stemness and dormancy, positioning it as a potential therapeutic target for metastatic and refractory cancers." (PMID 39716976, 2025).
cancer (continued). "In this study, we found that nuclear TRAF4 expression was higher in multiple human cancer tissues and cell lines compared with their matched normal tissues and cells." (PMID 39716976, 2025). "TRAF4 promotes the proliferation, invasion, and survival of cancer through the Akt, Wnt/β-catenin, and MAPK pathways." (PMID 39710325, 2024). "In contrast, TRAF4 is only enriched in 3 pathways, namely pathways in cancer, small cell lung cancer, and IL-17 signaling pathway." (PMID 36944688, 2023). "Emerging evidence indicates that TRAF4 plays an essential role as an oncogene in cancer development." (PMID 36625999, 2023). "It has been shown that TRAF4 is highly expressed in a variety of cancer types and promotes cancer cell proliferation, metastasis, and chemoresistant through signaling pathways such as NF-κB, AKT, Wnt/β-catenin and CHK1." (PMID 36765039, 2023). "TRAF4 is upregulated in various cancers and plays a vital role in cancer development and drug resistance." (PMID 36625999, 2023). "The finding that TRAF4 is highly expressed in metastatic PC not only expand the role of the ubiquitination system in human cancers, but also identifies TRAF4 as a new clinical biomarker, predictor of TrkA hyperactivation and PC aggressiveness." (PMID 36941697, 2023). "TrkA (a neurotrophin RTK) was identified as a TRAF4-targeted ubiquitination substrate that promotes cancer cell invasion, and inhibition of TrkA activity abrogates TRAF4-dependent cell invasion." (PMID 35242717, 2022). "DLEU1 can act as a competitive endogenous RNA that promotes elevated TRAF4 expression levels, promotes cancer cell proliferation through the Hippo signaling pathway and Wnt/β-catenin signaling pathway and regulate cell migration." (PMID 35242717, 2022). "TRAF4 recruits the TJs and prevents their formation and stabilization, facilitating cell migration that allows cancer progression." (PMID 35242717, 2022). "TRAF4, a member of the TNF receptor-related factor family, encodes a 54 kD connexin consisted of 470 amino acid, is highly expressed in a variety of cancer cells." (PMID 35054492, 2022). "Several signalling pathways that are dependent on TRAF4/5 have been suggested to be involved in cancer, with evidence from studies of cultured human cancer cells or their xenografts in immunodeficient mice and patient samples." (PMID 34983361, 2022). "Reducing TRAF4 can inhibit cancer cell proliferation, invasion and metastasis by downregulating the AKT signaling pathway, inhibiting the NF-κB pathway and engaging in RSK4 interactions." (PMID 35242717, 2022). "DR6 binding to TRAF4 enhances cancer cell mobility by enhancing MMP2 and MMP9 expression and participating in the PI3K/AKT pathway." (PMID 35242717, 2022). "TRAF4 significantly enhances cancer development and progression in various malignancies, and its effects involve multiple signaling pathways such as AKT, NF-κB, Wnt, TGF-βand TNF-α." (PMID 35242717, 2022). "High expression of TRAF4 significantly increased cyclinD1 and c-myc protein expression levels in cancer cells and activated the Wnt/β-catenin signaling pathway." (PMID 35242717, 2022). "Previous studies showed that the TRAF4‐mediated ubiquitination and the activation of Akt were involved in the cellular glycolysis of cancer cells." (PMID 35748027, 2022). "TRAF4 is a potential molecular target for cancer prevention and treatment, and the regulatory mechanism of TRAF4 needs to be further investigated." (PMID 35242717, 2022). "In the past few years, multiple studies revealed that TRAF4 is engaged in several signaling pathways and has essential biological functions in the generation and development of carcinoma." (PMID 35748027, 2022).